FTO (FTO alpha-ketoglutarate dependent dioxygenase)
Diseases named in the same sentence as FTO in open-access papers (continued):
Sharing a sentence is not in itself a finding about the gene and the disease.
Obesity (continued). "A number of subjects included in the normal groups were discovered to carry the homozygous mutant (A/ A) FTO genotype, thus a high genetic obesity predisposition." (PMID 25866584, 2015). "FTO rs993969 genotyping was performed on two individual groups selected based on specific criteria associated with obesity diagnosis and comorbidities." (PMID 25866584, 2015). "rs9939609 is the most frequently studied intronic SNP of FTO but its frequency and association with obesity are controversial due to contradictory results among different population." (PMID 26357660, 2015). "Polymorphisms in the FTO gene have been shown to be associated with obesity in different ethnic groups of European and other ancestries." (PMID 25647475, 2015). "In fact, obesity-related risk allele carriers of FTO gene show dose-dependent increments in BMI during aging." (PMID 26691922, 2015). "Our team has found that several polymorphisms in the FTO gene, the locus conferring the highest genetic risk contribution to obesity, are associated with increased BMI in people with MDD." (PMID 25903154, 2015). "Two human demethylases, the fat mass and obesity-associated (FTO) enzyme and ALKBH5, oxidatively demethylate abundant N6-methyladenosine (m6A) residues in mRNA." (PMID 25452335, 2015). "Single nucleotide polymorphisms (SNPs) in the first intron of FTO are highly associated with obesity and obesity-related traits." (PMID 26691922, 2015). "Data from over 200,000 individuals were required to confirm the attenuation of FTO obesity risk genotype by physical activity with the reported interaction term significant, Pinter = 0.001, because only one candidate gene was tested." (PMID 25811787, 2015). "For example, results from a UK study using the polymorphism of the FTO gene as an instrumental variable for obesity, provided evidence that obesity is a risk factor for the development of common mental disorders." (PMID 26167892, 2015). "A grasp of its regulatory function was missing, however, until the discovery of the fat mass and obesity-associated (FTO) enzyme in 2011." (PMID 25452335, 2015). "FTO (fat mass and obesity associated gene) was genetically identified to be associated with body mass index (BMI), presumably through functional regulation of energy homeostasis." (PMID 26218273, 2015). "Peripheral blood cells from homozygous (AA) subjects for the FTO “obesity-risk” rs9939609 variant exhibited increased FTO mRNA, reduced ghrelin m6A mRNA, and increased ghrelin mRNA abundance." (PMID 26691922, 2015). "For both ABFs and P‐values, the strongest evidence of an overlap association with both obesity and osteoarthritis is a variant in FTO, which is unequivocally associated with adiposity [Fawcett and Barroso, 2010]." (PMID 26411566, 2015). "FTO, fat mass- and obesity-associated gene (MIM 612938) maps to chromosome 16q12.2 and is widely expressed in a variety of human tissues with highest levels detected in the brain, pancreatic islets, and the liver." (PMID 26691922, 2015). "Although FTO is most probably the strongest and best replicated obesity gene, different GWAS studies for obesity-related traits in populations with European ancestry identified different FTO SNPs, with rs9939609 most commonly associated to obesity." (PMID 25890290, 2015). "FTO is an established obesity-susceptibility gene, and several loci in this gene have been reported to be associated with cancer risk." (PMID 26146447, 2015). "The strongest genetic association with risk to polygenic obesity are single-nucleotide variants in intron 1 and 2 of the FTO (fat mass and obesity associated) gene." (PMID 26557137, 2015). "A recent study in children demonstrated that the rs9939609 single-nucleotide polymorphism in the fat mass and obesity (FTO) gene influences prospective weight gain, however, only in those who were vitamin D-deficient." (PMID 25724814, 2015).
Obesity (continued). "The purpose of this mini review is to shed light on these new studies of FTO function in adipose tissue and present a clearer picture of its impact on obesity susceptibility." (PMID 26788058, 2015). "A number of studies highlighted the benefits of the Mediterranean diet plan in individuals carrying a genetic predisposition for developing obesity in general or the specific FTO predisposition." (PMID 25866584, 2015). "Further advances in the mRNA methylation field were catalysed by the discovery that FTO (Fat Mass Obesity), the most frequently associated gene with obesity, is an mRNA m6A adenosine demethylase." (PMID 26186436, 2015). "The first overall obesity GWAS identified a robust association between BMI and SNPs in the first intron of the fat mass and obesity-associated (FTO) gene that has been widely replicated since." (PMID 26363598, 2015). "The homozygous FTO risk allele (rs9939609, A allele) increases the risk of obesity by approximately 1.7 fold." (PMID 25830347, 2015). "An interaction of the obesity-associated intronic region of FTO and the promoter sequence of Iroqouis 3 (IRX3) has recently been identified." (PMID 26431034, 2015). "For example, the fat mass and obesity associated gene (FTO) seems to be present only in marine algae and vertebrates, which is a highly unusual distribution." (PMID 25785303, 2015). "There is compelling evidence that FTO is one of the world ́s major risk genes increasing BMI and promoting obesity." (PMID 26691922, 2015). "The A/T polymorphism (rs9939609) in the fat mass and obesity associated (FTO) gene, was discovered in two separate GWAS, and is an example of specific variant associated with obesity, 2TD, and physical activity levels." (PMID 25612568, 2015). "Brennan reported that the rs9939609 A allele, for the obesity genetic marker FTO gene, which is linked with increased BMI, was associated with a decreased risk of lung cancer." (PMID 25820198, 2015). "Each FTO risk allele increases BMI by 0.26–0.66 kg/m2, equivalent to ~0.84–2.1 kg in body weight for a 1.80-m-tall person, and the risk of obesity by 1.25–1.32 odds." (PMID 25724814, 2015). "The purpose of this review is to examine the emerging role of FTO in adipose tissue and its relevance to obesity susceptibility." (PMID 26788058, 2015). "Loss of function FTO mutations significantly impact body composition in humans and mice, with Fto-deficient mice reported to resist the development of obesity in response to a high-fat diet (HFD)." (PMID 25830092, 2015). "The fat mass and obesity-associated gene (FTO), located on chromosome 16q12.2, has been identified by large-scale genome-wide association studies and is recognized to be associated with both body mass index (BMI) and obesity." (PMID 26032905, 2015). "Previously, genetic variants within FTO have been identified to exhibit the strongest association with obesity in humans." (PMID 26715945, 2015). "Variants at FTO locus confer the largest genetic effect size among all obesity susceptibility loci and was robustly replicated in multiple populations and under various study designs." (PMID 25793382, 2015). "Single-nucleotide polymorphisms within intron 1 of the FTO (fat mass and obesity-associated) gene are associated with enhanced FTO expression, increased body weight, obesity and type 2 diabetes mellitus (T2DM)." (PMID 26691922, 2015). "Intron 1 of the gene is the only one associated with obesity, multiple FTO gene variants being at that location which is correlated to this disorder: rs9939609, rs17817449, rs1421085, rs9930506, rs8050136, rs9751812, rs9751812 and other 25 validated SNPs." (PMID 25866584, 2015). "Polymorphisms in the FTO gene, which are linked to obesity, have been found to be linked to reduced sensitivity to satiety, which leads to overeating." (PMID 25698918, 2015). "The results of our study revealed important links between the FTO genetic predisposition for obesity and the development of the disorder itself." (PMID 25866584, 2015).
Obesity (continued). "Adult obesity susceptibility variants including FTO conferred a faster tempo of height growth that was evident before puberty." (PMID 26691922, 2015). "As a result of the persistent association with obesity in this region, the function of the nearest gene, FTO, has been under close scrutiny." (PMID 26642925, 2015). "DRD2 exhibits effects on weight gain from normal weight to overweight/obesity in adults, while, FTO is associated to weight gain from adolescence to young adulthood." (PMID 26445370, 2015). "As an illustration, the obesity-associated FTO sequence directly interacts with the promoters of IRX3 as well as FTO in the human, mouse and zebrafish genomes." (PMID 25825681, 2015). "Genome-wide association studies (GWAS) have indicated that single nucleotide polymorphisms (SNPs) on chromosome 16 within the first intron of FTO (FaT mass and Obesity related) are robustly associated with human obesity." (PMID 25830092, 2015). "Frayling and co-workers showed for the first time the contribution of the SNP rs9939609 in fat mass and obesity-associated gene FTO on excess of weight." (PMID 25928419, 2015). "Recently, several studies have reported associations between fat mass and obesity-associated (FTO) gene mutations and cancer susceptibility." (PMID 26146447, 2015). "Among them, the fat mass and obesity associated (FTO) gene was consistently and reliably replicated in different studies." (PMID 25903154, 2015). "Emerging evidence, however, implicates adipose tissue development and function in the causal relationship between perturbations in FTO expression and obesity." (PMID 26788058, 2015). "Despite the large size of FTO gene, variants implicated in obesity and weight gain are largely located in the first intron." (PMID 26357660, 2015). "The fat mass and obesity-associated (FTO) gene plays a pivotal role in regulating body weight and fat mass; however, the underlying mechanisms are poorly understood." (PMID 25881961, 2015). "The genetic FTO rs9939609 obesity predisposition can be cancelled with constant life-long physical exercise and diet." (PMID 25866584, 2015). "Polymorphisms in the first intron of FTO have been robustly replicated for associations with obesity." (PMID 25647475, 2015). "A meta-analysis of the FTO gene in East Asians (17,255 case and 19,703 control subjects) has shown variants of FTO associated with both obesity and T2D." (PMID 24637646, 2014). "The association of the FTO rs9939609 variant with both increased BMI and obesity-related phenotypes has been examined by independent studies of large Caucasian populations." (PMID 25110886, 2014). "Both enzymes appear to be physiologically important: FTO is associated with obesity, whereas ALKBH5 is involved in fertility." (PMID 24489119, 2014). "A total of 45 SNPs located in the FTO gene demonstrated significant associations with obesity phenotypes using a Bonfferoni corrected significance level of P<1.68×10−5." (PMID 24879436, 2014). "The fat mass and obesity associated (FTO) gene was the first identified gene through genome-wide association studies (GWAS)." (PMID 25251416, 2014). "While several previous studies reported association between FTO SNPs and obesity-related phenotypes in Hispanic Americans, African Americans and Asian populations, these studies were relatively small in sample sizes and showed mixed results." (PMID 24879436, 2014). "Since the FTO gene was first identified in 2007, many subsequent studies have also demonstrated an association of FTO genetic variants with obesity and body mass index (BMI) in various ethnic populations in both children and adults." (PMID 25110886, 2014). "Increased expression of FTO is likely underlying this obesity phenotype, as mice with two additional copies of Fto (FTO-4 mice) exhibit increased adiposity and are hyperphagic." (PMID 24842286, 2014).
Obesity (continued). "The risk alleles for obesity (“A” allele for the rs9939609 FTO variant and “G” allele for the rs9930506 FTO variant) were associated with low weight at birth." (PMID 25539997, 2014). "Our findings in this multiethnic population confirmed the importance of the FTO gene for obesity risk in humans." (PMID 24879436, 2014). "Another 125 SNPs out of the 1,275 total SNPs spanning the FTO gene in the present study showed marginal associations with obesity phenotypes (meta-analysis P-values ranging from 1.71×10−5 to 4.99×10−2) (Results not shown)." (PMID 24879436, 2014). "Nevertheless, several studies demonstrated a clear correlation between genetic variations of the FTO gene and an early development of obesity, which is the main cause for the metabolic syndrome." (PMID 25144618, 2014). "In the present study, FTO variants that confer a predisposition to obesity later in life appeared to be associated with a low weight at birth." (PMID 25539997, 2014). "The major novel finding in our study is the inverse association between the obesity associated A allele of rs9939609 in the FTO gene and completed suicide." (PMID 25265168, 2014). "In conclusion, in this study, we confirmed the role of FTO on genetic susceptibility to obesity and discovered two new FTO obesity-related SNPs (rs7206790 and rs11644943), in Chinese school-age population." (PMID 25251416, 2014). "This study confirms the association of FTO rs9939609 with obesity and dietary preferences in Chinese Han children and adolescents." (PMID 25110886, 2014). "The pattern and age of onset of the association between FTO rs9939609 and BMI/obesity from childhood to adolescence in a Chinese population are not clear." (PMID 24827155, 2014). "Sex-specific Associations of FTO rs9939609 with BMI a and Obesity b from Childhood into Adolescence among the Sub-cohort of 777 Children." (PMID 24827155, 2014). "Recent studies have shown that the SNPs in FTO that are associated with obesity regulate IRX3 expression, which is highly expressed in the brain." (PMID 25177340, 2014). "In the sub-cohort of 777 children, the association of FTO with BMI and obesity was examined at baseline and during follow-up." (PMID 24827155, 2014). "Previous studies have suggested that fat mass-and obesity-associated (FTO) gene is associated with body mass index (BMI) and the risk of obesity." (PMID 24911064, 2014). "Although the results were not statistically significant in other studies.We confirmed that FTO rs9939609 was strongly associated with obesity-related metabolic traits such as WC, fasting glucose, LDL-C and HDL-C after adjusting for age, gender and location." (PMID 25251416, 2014). "The association of the rs9939609 single nucleotide polymorphism in FTO gene with obesity has been extensively investigated in studies of populations of European, African, and Asian ancestry." (PMID 25110886, 2014). "The purpose of the present study was to examine the association of the FTO rs9939609 polymorphism with the risk of obesity and obesity-related traits in children and adolescents from different areas of China." (PMID 25110886, 2014). "FTO was found to be a obesity-risk gene in humans and FTO deficiency in mice led to reduction in adipose tissue." (PMID 25144618, 2014). "In the present study, FTO rs9939609 was found to be significantly associated with the risk of obesity and also with dietary preferences independently of BMI." (PMID 25110886, 2014). "Common intronic variants in the Human fat mass and obesity-associated gene (FTO) are found to be associated with an increased risk of obesity." (PMID 24503721, 2014). "This is the first observation of such an inverse relationship between birth weight and FTO risk alleles for obesity in full-term, singleton, healthy newborns." (PMID 25539997, 2014). "Overexpression of FTO correlates with increased food intake and obesity, whilst loss-of-function results in lethality and severe developmental defects." (PMID 24503721, 2014).
Obesity (continued). "Conversely, the other study described a positive association between the obesity related FTO variant and depression/anxiety which was present among 2,981 men but not 1,164 women from population of The Whitehall II Study." (PMID 25265168, 2014). "The fat mass and obesity associated gene (FTO), located in chromosome 16q12.2 and expressed in the adipose tissue and the brain and muscles, was proved to associate with body mass index and obesity." (PMID 24466303, 2014). "Genome-wide association studies linked common polymorphisms in the first intron of FTO to body mass index, risk of obesity, type 2 diabetes, polycystic ovary syndrome and cardiovascular diseases." (PMID 25014650, 2014). "Recent work on obesity-associated variants in the dioxygenase FTO highlights this and illustrates further approaches that can be used to investigate GWAS signals and the functional significance of regulatory variants." (PMID 25473428, 2014). "Further studies on other polymorphisms from FTO and increasing the sample size are needed, to establish the genetic basis contributing to the risk of obesity in Chinese population." (PMID 24911064, 2014). "Recent interest in the FTO gene stems from studies demonstrating an association between a single nucleotide polymorphism in the first intron of the gene with obesity-related traits and higher obesity risk in different human populations." (PMID 24743632, 2014). "Recently, further evidence has suggested that FTO interacts with energy intake patterns in children, as related to obesity risk." (PMID 25110886, 2014). "In 2007, studies confirmed the fat mass and obesity‐associated (FTO) gene as the first genome‐wide association study (GWAS)‐identified obesity susceptibility gene." (PMID 25501432, 2014). "The genetic polymorphisms rs9939609 and rs8050136 within the FTO gene were found to be significantly associated with obesity in different populations, including the Chinese population." (PMID 25377722, 2014). "The present study aimed to assess the association of FTO rs9939609 with body mass index (BMI) and the risk of obesity from childhood to adolescence, and to determine the age at which the association becomes evident." (PMID 24827155, 2014). "Few studies have been conducted to examine the relationship of FTO variants with obesity in Asian children and adolescents, particularly in large childhood populations." (PMID 25110886, 2014). "Genome-wide association studies (GWAS) have initially identified the FTO gene as a gene strongly associated with obesity." (PMID 24626192, 2014). "Studies have described the association between FTO and obesity, while the association between T2D and FTO is debated." (PMID 25177340, 2014). "The current study also showed that the associations of the rs9939609 A allele in FTO with BMI and obesity were stronger in girls than in boys, and the associations persisted into late puberty in girls but not in boys." (PMID 24827155, 2014). "The fat mass- and obesity-associated gene (FTO) was the first, well-replicated gene to be associated with common obesity in both adults and children from various ethnic backgrounds." (PMID 24827155, 2014). "In conclusion, the present findings suggest that the association between common variant rs9939609 in the FTO gene and obesity-related traits becomes evident after 12–14 years of age." (PMID 24827155, 2014). "The limitation of both studies is that they consider the demethylase activity of FTO as relevant for its association with obesity." (PMID 25144618, 2014). "This gene, now known as FTO (fat mass and obesity associated, Gene ID: 79068), has been repeatedly found to affect obesity in different populations." (PMID 25377722, 2014). "Recently, obesity in adults was found to be associated with common variants of the fat mass and obesity-associated (FTO) gene." (PMID 25539997, 2014). "This is the first study to examine age-related association between FTO rs9939609 and obesity-related traits in Chinese children." (PMID 24827155, 2014).